FAM124B (family with sequence similarity 124 member B)
Synonyms: FLJ22746
Tractability: No criterion of Open Targets' tractability assessment is met for any kind of drug.
Gene: Protein-coding gene on chromosome 2 (224,376,821 to 224,402,107, reverse strand). Ensembl gene ENSG00000124019.
Subcellular location: Nucleus
Subcellular location (Human Protein Atlas): Nucleoplasm; Mitochondria
Pathways (Reactome):
Chromatin organization: CHD6, CHD7, CHD8, CHD9 subfamily
Gene Ontology:
Molecular function: protein binding
Cellular component: nucleoplasm; nucleus
Genetic constraint (gnomAD): Loss-of-function variants: 18 observed, 21.49 expected, observed/expected ratio (o/e) 0.84, 90% interval 0.58 to 1.24. The upper end of that interval is the gene's LOEUF score, 1.24, which puts it in group 5 of 6, group 1 being the genes least tolerant of losing a copy. Missense variants: 540 observed, 584.45 expected, observed/expected ratio (o/e) 0.92, 90% interval 0.86 to 0.99. Synonymous variants: 223 observed, 238.09 expected, observed/expected ratio (o/e) 0.94, 90% interval 0.84 to 1.05.
Homologues: Orthologues: chimpanzee FAM124B (98% identical), macaque FAM124B (93% identical), pig FAM124B (75% identical), rabbit FAM124B (74% identical), guinea pig FAM124B (66% identical), rat Fam124b (66% identical), mouse Fam124b (65% identical), zebrafish fam124b (37% identical), tropical clawed frog fam124b (36% identical). Paralogues in human: FAM124A (30% identical).
Diseases named in the same sentence as FAM124B in open-access papers:
FAM124B is named in the same sentence as 14 diseases in open-access papers, as found by Europe PMC text mining. Sharing a sentence is not in itself a finding about the gene and the disease. The quoted sentences say what the papers report.
acute lymphoblastic leukemia (1 paper, 2016). Leukemia with an acute onset, characterized by the presence of lymphoblasts in the bone marrow and the peripheral blood. "For the interaction partner of FAM124B, CHD8, one study so far described an oncogenic role in a mouse model for BCR-ABL1+ acute lymphoblastic leukemia, while neither the role of FAM124B nor its interaction with CHD7/8 have been described so far in AML." (PMID 27585840, 2016).
alcohol dependence (1 paper, 2024). Physical and psychological dependence on alcohol. "Moreover, FAM124B is related to anorexia nervosa, and AVPI1 is associated with alcohol dependence." (PMID 39020437, 2024).
autism spectrum disorder (1 paper, 2012). A spectrum of developmental disorders that includes autism, and Asperger syndrome. "Furthermore, the high Fam124B expression in the developing mouse brain and in neuronal tissues at embryonic day E12.5 might indicate a role of FAM124B together with CHD8 in neurodevelopmental and autism spectrum disorders." (PMID 23285124, 2012).
cerebellar ataxia (1 paper, 2025). A neurological syndrome characterized by clumsy and uncoordinated movement of the limbs, trunk, and cranial muscles. "FAM124B has been proposed to be an important protein involved in neurodevelopmental disorders, while SPG7 mutations have been linked to spastic paraplegia and cerebellar ataxia." (PMID 40051167, 2025).
CHARGE syndrome (1 paper, 2012). CHARGE syndrome is a multiple congenital anomaly syndrome characterized by the variable combination of multiple anomalies, mainly Coloboma; Choanal atresia/stenosis; Cranial nerve dysfunction; Characteristic ear anomalies (known as the major 4 C's). "Due to the fact that CHARGE syndrome is a developmental disorder and NDD/ASD are caused by abnormal brain development, we extended our Fam124B expression studies to embryonic tissues." (PMID 23285124, 2012). "Similar to the results of adult mouse tissues, Fam124B expression at E12.5 correlated in many embryonic tissues with the Chd7 expression pattern, and therefore Fam124B was found to be expressed in organs affected in CHARGE syndrome." (PMID 23285124, 2012). "From the overlapping expression pattern between Chd7 and Fam124B at murine embryonic day E12.5 and the high expression of Fam124B in the developing mouse brain, we conclude that Fam124B is a novel protein possibly involved in the pathogenesis of CHARGE syndrome and neurodevelopmental disorders." (PMID 23285124, 2012). "The results of our interaction studies, the subcellular localization, and expression profile of FAM124B provide valuable information and represent a starting point for further functional investigations on FAM124B and its possible role in CHARGE syndrome and NDD/ASD." (PMID 23285124, 2012). "Therefore, we assume a role for FAM124B in the pathogenesis of CHARGE syndrome and NDD/ASD." (PMID 23285124, 2012).
lung adenocarcinoma (1 paper, 2026). A carcinoma that arises from the lung and is characterized by the presence of malignant glandular epithelial cells. "Applied to primary lung adenocarcinoma, SpliCOOL-seq identified tumour subclones within the tumour lesion and uncovered novel DNA methylation biomarkers (e.g., FAM124B, SFN, OR7E47P) associated with patient survival." (PMID 41603298, 2026).
psoriasis (1 paper, 2021). An autoimmune condition characterized by red, well-delineated plaques with silvery scales that are usually on the extensor surfaces and scalp. "Particularly, the mast cells makers IL1B is significantly up-regulated in PP, while FAM124B and FAM174B is down-regulated in PP, indicating the mast cells are indeed activated in psoriatic skin and they may play a role in the progression of psoriasis." (PMID 34887864, 2021).
neurodevelopmental disorder (3 papers, 2012 to 2025). A behavioral and cognitive disorder with onset during the developmental period that involves impaired or aberrant development of intellectual, motor, or social functions. "FAM124B is involved in the pathology of neurodevelopmental disorders." (PMID 40331981, 2025).
tumor (2 papers, 2011 to 2026). "A recent genomic methylation analysis of 12 ER+ and 12 ER− tumors identified 5 loci that are consistently hypermethylated in one or the other tumor type (MANEAL, PER1, NAV1, FAM124B, and ST6GALNAC1)." (PMID 21364760, 2011).
cancer (1 paper, 2017). A tumor composed of atypical neoplastic, often pleomorphic cells that invade other tissues. "Similar associations with ERG have also been found for other FAM members, including FAM77C and FAM13A that are up regulated in the presence of ERG, or for FAM111B, FAM3B and FAM124B that are down-regulated in ERG positive cancers." (PMID 28415558, 2017).
FAM124B also shares sentences with these, for which no sentence is quoted: anorexia nervosa (1 paper); neurological disease (1); pneumonia (1); Spastic paraplegia (1).